MMP3 (matrix metallopeptidase 3)
Diseases named in the same sentence as MMP3 in open-access papers (continued):
Sharing a sentence is not in itself a finding about the gene and the disease.
dysplasia (2 papers, 2012 to 2025). A usually neoplastic transformation of the cell, associated with altered architectural tissue patterns. "In our study we tried to assess the potential of MMP-3, MMP-7, MMP-10, and MMP-26, which showed significant differences in concentrations between the groups of healthy women, dysplasia patients, and cancer patients, and also demonstrated the ability to distinguish benign from malignant lesions." (PMID 41462922, 2025).
familial hypercholesterolemia (2 papers, 2023 to 2025). An inheritable form of hyperlipidemia, in which there are excess lipids in the blood. "Several studies have shown increased MMP-3 levels in atherosclerotic plaques and in the circulation of individuals with hypercholesterolemia." (PMID 39445733, 2025). "Analysis of Open Targets and other databases indicated evidence of drug development, including phase II-IV trials, for 6 proteins (PGF, ASGR1, F2R, TFPI, tenascin, and MMP3), with 3 related to CVD outcomes or traits (F2R for MI, TFPI for ICH, and ASGR1 for familial hypercholesterolemia)." (PMID 37940228, 2023).
Fever (2 papers, 2021 to 2023). Body temperature elevated above the normal range. "The concentration of MMP-2, MMP-3, MMP-9, MMP-13, TIMP-1, and FG-α in the KD group were significantly higher than those in the fever group (p < 0.05).The KD group was divided into two subgroups, patients with combined CAL and 179 patients without combined CAL." (PMID 37575991, 2023). "The concentration of MMP-2, MMP-3, MMP-9, MMP-13, TIMP-1, and FG-α in the KD group were significantly higher than those in the fever group (p < 0.05)." (PMID 37575991, 2023).
fungal infection (2 papers, 2024 to 2025). "For example, a crucial member of the MMP family, matrix metalloproteinase 3 (MMP-3), often referred to as stromelysin-1, is highly expressed in the infectious milieu and serves as the basis for targeted medication delivery against fungal infections." (PMID 41333023, 2025).
gingivitis (2 papers, 2021 to 2023). A disorder involving inflammation of the gums; may affect surrounding and supporting structures of the teeth. "A study revealed that matrix-metalloproteinase 3 (MMP-3), MMP-8, and IL-1β in gingival crevicular fluid and whole saliva of gingivitis patients remained insignificantly altered over 8 weeks of OIs use." (PMID 36834421, 2023).
glomerulonephritis (2 papers, 2016 to 2019). A renal disorder characterized by damage in the glomeruli. "It has been reported previously that both thrombin and MMP-3 are activated in the pathophysiology of glomerulonephritis." (PMID 27992535, 2016).
Hepatitis (2 papers, 2020 to 2021). Inflammation of the liver. "Next, we examined the gene expression of two candidate genes having the extreme breakpoints identified by Trendy, namely, matrix metallopeptidase 3 (Mmp3) and arylacetamide deacetylase (Aadac) in the liver tissues of ConA-induced hepatitis model mice." (PMID 33221747, 2020).
infarct (2 papers, 2021 to 2024). "MMP-3 expression levels in both the control and r-tPA groups were negatively correlated with infarct volume and swelling while only the control group’s MMP-3 levels were negatively correlated with hemorrhage." (PMID 39273389, 2024). "In the peri-infarction area, MMP-3-positive neurons exhibited a strong immune response, a large number, and a long course, reaching a peak on the third day and continuing until the seventh day." (PMID 34790277, 2021). "We found that MMP-3 was mainly expressed in neurons and microglia in the ischaemic infarction area, similar to previous findings." (PMID 34790277, 2021). "Reportedly, MMP-3 positive microglia mainly exist in the infarction centre 4–7 d after reperfusion in a rat cerebral ischaemia 50 min reperfusion model." (PMID 34790277, 2021). "In the central part of the infarction, MMP-3-positive neurons mainly appeared before 24 h and disappeared after 3 d, which was related to the necrosis and disintegration of most of the neurons in the infarction area." (PMID 34790277, 2021).
interstitial lung disease (2 papers, 2023 to 2025). A diverse group of lung diseases that affect the lung parenchyma. "Genetic studies show that polymorphisms in MMP-1 and MMP-3 are linked to distinct clinical phenotypes: for example, the MMP-1 1G/1G genotype correlates with interstitial lung disease, while the MMP-3 5A/5A variant is associated with anti-topoisomerase antibodies." (PMID 41226358, 2025).
intestinal tumors (2 papers, 2003 to 2019). "A number of different MMPs may be important in intestinal tumour formation as human tumours have been shown to express interstitial collagenase (MMP-1), gelatinase A (MMP-2), stromelysin 1 (MMP-3), matrilysin (MMP-7), gelatinase B (MMP-9), and stromelysin 3 (MMP-11)." (PMID 12778076, 2003).
kidney cancer (2 papers, 2022 to 2025). Primary or metastatic malignant neoplasm involving the kidney. "We compared two of them—MMP-3 (stromelysin-1) and MMP-10 (stromelysin-1)—in human kidney cancer with the parts of the same organ that were unaffected." (PMID 36231910, 2022).
kidney damage (2 papers, 2024 to 2025). "Among the different types of MMPs, MMP-1, MMP-2, and MMP-3 have been identified as particularly important in the progression of kidney damage." (PMID 40649789, 2025). "Individuals carrying certain genotypes of MMP-3 are thought to be more affected by nephropathy in T2D." (PMID 39000435, 2024). "MMP-3 could be valuable as a complement to other analyses to assess kidney damage." (PMID 39000435, 2024). "This study aims to investigate plasma MMP-3 and GDF-15 as systemic biomarkers for diabetic neuropathy and nephropathy in T1D." (PMID 39000435, 2024). "In this study, the intention was to investigate the potential of MMP-3 and GDF-15 as biomarkers for neuropathy and nephropathy in T1D." (PMID 39000435, 2024). "The purpose of this study is to examine whether circulating MMP-3 and GDF-15 can be used as biomarkers for detecting and monitoring diabetic neuropathy and/or nephropathy in T1D." (PMID 39000435, 2024).
kidney failure (2 papers, 2021 to 2024). An acute or chronic condition that is characterized by the inability of the kidneys to adequately filter the blood. "The MMP-3 level can be related to kidney function expressed by eGFR, therefore its elevation should be interpreted with caution in patients with kidney failure." (PMID 33664330, 2021). "MMP-3 level can be related to kidney function expressed by eGFR, therefore its elevation should be interpreted with caution in patients with kidney failure." (PMID 33664330, 2021).
liver disease (2 papers, 2022). "We propose that the concentration of MMP-3 in sera, in connection with the level of bilirubin and presence of specific antibodies could be used as a non-invasive biomarker to determine the possible severity of liver disease." (PMID 35529854, 2022). "A number of these analytes were differentially expressed related to liver disease, including proteins with inflammatory and immunomodulatory activities, such as CCL15, pentraxin-3, TRAIL and MMP-3, among others, as well as the growth factors M-CSF, SCF, SCFG-β and HGF." (PMID 36230823, 2022).
lupus nephritis (2 papers, 2019). Glomerulonephritis in the context of systemic lupus erythematosus. "Secondly, the results showed that MMP-3 was significantly elevated in patients with renal involvement, both in histologically proven lupus nephritis and mere proteinuria." (PMID 31396295, 2019). "Our results and previous works suggested that serum MMP-3 levels may reflect the presence and possibly histological severity of lupus nephritis in patients with SLE." (PMID 31396295, 2019). "The meta-analysis showed that MMP-3 levels were significantly higher in the lupus nephritis group than in the nonnephritis group (P = 0.003, Hedges' g: 0.639, 95% CI 0.221-1.057)." (PMID 31396295, 2019).
meningioma (2 papers, 2023 to 2024). A generally slow growing tumor attached to the dura mater. "In meningiomas, the protein levels of MMP1, MMP2, and MMP3 were similar to controls, but a slight decrease in MMP8 protein levels was identified." (PMID 38474106, 2024).
meningitis (2 papers, 2013 to 2019). A disorder characterized by acute inflammation of the meninges of the brain and/or spinal cord. "A moderate correlation between viral load in CSF and the levels of MMP-3 in CSF in the VZV patients was shown (p = 0.007) which was slightly more pronounced in the patients with meningitis (p = 0.002)." (PMID 30777092, 2019).
myocarditis (2 papers, 2013 to 2021). Myocarditis is a condition that is characterized by inflammation of the heart muscle (myocardium). "The transcription of many MMPs, especially MMP-3, MMP-8 and MMP-9 are upregulated in the acute phase of CVB3-induced myocarditis." (PMID 34452454, 2021). "The ratio of TIMP-1/MMP-1 or MMP-3 expression was significantly increased (P < 0.05) indicating an increase of deposition of collagen proteins at the later stage of CVB3 myocarditis." (PMID 24023968, 2013).
myopia (2 papers, 2012 to 2021). "There have been two SNPs rs3025058 (MMP3) and rs17576 (R279Q; MMP9) previously associated with myopia." (PMID 23077567, 2012). "In the case of common myopia there has been one study in a Caucasian cohort that assessed selected SNPs in MMP1, MMP3 and MMP9 and found a positive association of myopia with the rs3025058 in MMP3 (p = 0.015) and the rs17576(R279Q) in MMP9 (p = 0.026)." (PMID 23077567, 2012). "These are in MMP2 for refractive error and in MMP3 and MMP9 for common myopia." (PMID 23077567, 2012).
nasal polyp (2 papers, 2020 to 2021). "Previous studies provided evidence for higher levels of MMP‐1, MMP‐2, MMP‐3, MMP‐7, MMP‐8, and MMP‐9 in nasal polyps." (PMID 34504680, 2021). "Tissue protein analysis confirmed elevated levels of these targets compared to controls, and increased MMP3 and MMP7 observed in CRS subjects with nasal polyps compared to CRS subjects without polyps." (PMID 33005006, 2020).
nephritis (2 papers, 2019 to 2020). Inflammation of renal tissue. "We compared serum MMP-3 levels in SLE patients with active nephritis (n = 53) and those without (n = 39)." (PMID 31396295, 2019). "In subgroup analyses, we found a significant elevation of MMP-3 in the patients with nephritis compared to those without (P = 0.006, Hedges' g: 0.611, 95% CI 0.611-1.704)." (PMID 31396295, 2019).
neuropathies (2 papers, 2009 to 2024). "MMP3 has recently been implicated in the inflammatory response and the immune reaction in some neuropathies." (PMID 20003309, 2009). "For MMP-3, a positive correlation was found only in the T1D group with neuropathy for systolic blood pressure." (PMID 39000435, 2024). "MMP-3 may be useful as biomarker for neuropathy in T1D with albuminuria." (PMID 39000435, 2024).
osteonecrosis (2 papers, 2017 to 2021). A none disease characterized by death of bone tissue due to a lack of blood supply. "In addition, cartilage degeneration may happen during latestage steroid-induced osteonecrosis of the femoral head, after bone tissue collapse.Thus, we postulate that MMP3 is related to ONFH." (PMID 29312574, 2017). "Furthermore, another study also indicated that oral administration of Ok-PDRN inhibited the expression of IL-1β, matrix metalloproteinase (MMP)-3, and MMP-7, as well as production of inflammatory mediators including COX-2, prostaglandin E2 (PGE2), and TNF-α in an MIA-induced osteonecrosis model." (PMID 34067499, 2021).
Osteopenia (2 papers, 2023). Osteopenia is a term to define bone density that is not normal but also not as low as osteoporosis. "In contrast, in a group of women with osteopenia, MMP-3 correlated negatively only with the BMD of the lumbar spine and ward angle." (PMID 38138968, 2023).
ovarian tumors (2 papers, 2013 to 2020). "However, using RNA-Seq and TCGA data, researchers found MMP-3 overexpression in high-stage and high-grade ovarian tumors compared to lower stages tumors." (PMID 33392094, 2020).
pancreatitis (2 papers, 2009 to 2024). Inflammation of the pancreas. "All eight nanobiosensors (arginase, cathepsin B, cathepsin E, MMP1, MMP3, MMP9, neutrophil elastase, and uPA) were used to measure enzymatic activity in serum samples from four different disease groups: localized pancreatic cancer, metastatic pancreatic cancer, pancreatitis, and a ‘healthy’ control." (PMID 40292193, 2024).
pressure ulcers (2 papers, 2015). "In addition, GM-CSF, IFN-γ, MMP-3, and TIMP-1 were not reported previously in the wound healing process, and those genes may have a role in development of the pressure ulcers." (PMID 26177082, 2015).
primary sclerosing cholangitis (2 papers, 2017 to 2022). "PBC subjects had greater MMP-3 levels than controls: 68.9 ± 62.6 vs 21.3 ± 7.4 ng/mL, p < 0.001 for healthy subjects; 68.9 ± 62.6 vs 22.7 ± 7.6 ng/mL, p = 0.022 for autoimmune hepatitis controls; and 68.9 ± 62.6 vs 37.2 ± 17.4 ng/mL, p = 0.002 for primary sclerosing cholangitis controls." (PMID 35529854, 2022).
pulpitis (2 papers, 2012 to 2021). Inflammation of the dental pulp. "In the mild irreversible pulpitis model, the regeneration of pulp tissue with its associated vasculature and nerves was observed until 14 days after sealing with MMP-3, followed by extracellular matrix formation in the regenerated pulp tissues until day 28, consistent with our previous report." (PMID 23285075, 2012). "The mild pulpitis model was assessed over the time course of wound healing and pulp tissue regeneration following MMP-3 treatment." (PMID 23285075, 2012). "Given the critical role of IL-6 in regulating the balance between the Treg and the Th17 cells, controlling IL-6 activities by MMP-3 is a potentially effective approach to treat not only mild irreversible pulpitis but also various chronic inflammatory diseases." (PMID 23285075, 2012). "We next investigated the potential therapeutic effects of MMP-3 on the mild and severe pulpitis models." (PMID 23285075, 2012). "In contrast, in the severe pulpitis model, the entire pulp tissues were necrotic at 14 days after both MMP-3 and saline treatments." (PMID 23285075, 2012). "At 14 and 28 days after the sealing of teeth that were treated with MMP-3 in the mild pulpitis model, the pulp tissues were regenerated over the amputated site." (PMID 23285075, 2012). "Next, we further analyzed these regenerated pulp tissue induced by MMP-3 on the mild pulpitis model." (PMID 23285075, 2012). "We therefore analyzed the expression levels of a Th1 cytokine (TNF-α) and a Th2 cytokine (IL-6) in the MMP-3 treated pulpitis tissues." (PMID 23285075, 2012). "We followed the histological progression of the mild pulpitis model for 7 days after treatment to further assess the function of MMP-3 in the inflamed pulp tissues." (PMID 23285075, 2012). "In the present study, immunofluorescence staining demonstrated that HA co-localized with SHAP and versican underneath the amputated site in pulpitis tissues treated with MMP-3 plus NNGH, NNGH alone or saline." (PMID 23285075, 2012). "In the severe pulpitis model, the pulp tissues exhibited necrosis at 3 days even after MMP-3 treatment." (PMID 23285075, 2012). "Immunofluorescence staining demonstrated that HA co-localized with SHAP and versican underneath the amputated site in pulpitis tissues treated with MMP-3 plus NNGH, NNGH alone or saline." (PMID 23285075, 2012). "We therefore examined the extracellular matrix changes underneath the amputated site induced by MMP-3 in mild pulpitis tissues 3 days after treatment." (PMID 23285075, 2012). "On the other hand, immunofluorescence staining also demonstrated lower-intensity SHAP staining in the MMP-3-treated pulpitis tissues." (PMID 23285075, 2012). "The IL-6 expression levels in the pulp tissues of the MMP-3-treated teeth were significantly reduced (35.52±9.08 pg/mg protein) at 3 days after sealing compared with the saline-treated teeth in the mild pulpitis model (78.95±10.09 pg/mg protein) (mean ± SEM)." (PMID 23285075, 2012). "MMP‐3 promotes pulp regeneration in mild irreversible pulpitis by inhibiting IL‐6 activity." (PMID 34585454, 2021). "However, in the same region in MMP-3-treated pulpitis tissues, HA did not co-localize with SHAP or versican." (PMID 23285075, 2012). "In contrast to the mild pulpitis model, the treatment with MMP-3 could not induce tissue regeneration once the inflammation reached the central pulp in the severe pulpitis model." (PMID 23285075, 2012). "The pulp tissues in the severe pulpitis model at 3 days after MMP-3 or saline-treated were already necrotic; we could not detect either IL-6 or TNF-α protein (data not shown)." (PMID 23285075, 2012).
renal fibrosis (2 papers, 2022 to 2023). A final common manifestation of a wide variety of chronic kidney diseases characterized by glomerulosclerosis and tubulointerstitial fibrosis. "Nr4a1 was observed to promote renal fibrosis in mice by activating tumor growth factor β-signaling and increasing collagen I/III/IV and MMP3." (PMID 38132237, 2023).
retinal detachment (2 papers, 2024). An eye emergency condition which may lead to blindness if left untreated. "Matrix metalloproteinase, MMP-3, was upregulated following retinal detachment." (PMID 38397833, 2024).
sacroiliitis (2 papers, 2018 to 2019). "Compared to SIJ controls, the subchondral microvessel density, number of CD68+ multinuclear osteoclasts, and the levels of VEGF, caspase-3, MMP-3, and TNF-α expressed at the interface of the bone and cartilage were significantly higher in patients with sacroiliitis." (PMID 29884210, 2018). "The current study investigated whether there were differences in ESR, CRP, and some biomarkers (MMP3, IL-17, IL-22, IL-23) in relation to clinical indices of disease activity and the presence/absence of sacroiliitis signs on X-rays and MRIs in an Italian cohort with early and confirmed axSpA." (PMID 31440510, 2019).
schizophrenia (2 papers, 2013 to 2015). A major psychotic disorder characterized by abnormalities in the perception or expression of reality. "These abnormalities of the humoral factors, including IL-6 and soluble MMP3 after polyI:C treatment, impair neuronal development, resulting in psychiatric disorders such as schizophrenia and ASD." (PMID 26633355, 2015).
Serous Ovarian Cancer (2 papers, 2025). "Matrix metalloproteinase 3 (MMP3) is overexpressed in High-Grade Serous Ovarian Cancer (HGSOC) and is associated with poor survival outcomes; however, its role in platinum resistance remains underexplored." (PMID 40362252, 2025). "In addition, higher concentrations of the tested markers (except for MMP-3) were found in both subgroups of serous ovarian cancer compared to benign lesions." (PMID 40565125, 2025).
skin malignant melanoma (2 papers, 2014 to 2022). "The present study was conducted to investigate the relation of MMP3 -1171insA polymorphism with skin malignant melanoma risk in a pilot case-control study of Bulgarian patients (n = 26) and unaffected controls (n = 172)." (PMID 26019576, 2014). "MMP3 was highly correlated with stage II skin melanoma (F value = 7.77, p = 4.85E-06)." (PMID 36226170, 2022).
tauopathies (2 papers, 2021 to 2023). "Nevertheless, activation of MMP3 is a hallmark of several tauopathies, including AD and familial FTD cases." (PMID 34669475, 2021). "Frontotemporal dementia (FTD) with TDP-43 pathology due to a C9orf72 expansion mutation was included to investigate whether MMP3 up-regulation is specific to pure tauopathies." (PMID 34669475, 2021). "Consistent with this notion, a recent report showed that MMP3 secretion is highly induced in microglia co-cultured with tau aggregate–containing neurons or in brains from patients with tauopathy." (PMID 37759245, 2023). "Among these secreted proteins, the active form of matrix metalloprotease 3 (MMP3) is not only highly induced in microglia by coculture with tau aggregate–containing neurons but also increased in the brains of P301S tau transgenic mice and in brains of patients with tauopathies." (PMID 34669475, 2021).